IRAG1 (inositol 1,4,5-triphosphate receptor associated 1)
Description:
Plays a role as NO/PRKG1-dependent regulator of IP3-induced calcium release; its phosphorylation by PRKG1 inhibits bradykinin and IP3-induced calcium release from intracellular stores. Recruits PRKG1 to the endoplasmic reticulum and may mediate the assembly of PRKG1 and ITPR1 in a macrocomplex. Involved in PRKG1 signaling cascade leading to inhibition of platelet activation and aggregation. Also mediates NO-dependent inhibition of calcium signaling in gastrointestinal smooth muscle contributing to NO-dependent relaxation. Plays a role in the regulation of cellular excitability by regulating the hyperpolarization-activated cyclic nucleotide-gated HCN4 channel activity (By similarity).
Synonyms: IRAG; JAW1L; MRVI1
Tractability: Antibody: UniProt predicts a signal peptide or a membrane-spanning region. PROTAC: ubiquitination databases record sites on it.
Gene: Protein-coding gene on chromosome 11 (10,573,091 to 10,693,988, reverse strand). Ensembl gene ENSG00000072952.
Subcellular location: Cytoplasm, perinuclear region; Sarcoplasmic reticulum; Membrane
Subcellular location (Human Protein Atlas): Cytosol; Nuclear bodies
Pathways (Reactome):
Hemostasis: cGMP effects
Gene Ontology:
Molecular function: protein binding
Cellular component: endoplasmic reticulum membrane; platelet dense tubular network membrane; membrane; perinuclear region of cytoplasm; sarcoplasmic reticulum
Genetic constraint (gnomAD): Loss-of-function variants: 55 observed, 93.26 expected, observed/expected ratio (o/e) 0.59, 90% interval 0.47 to 0.74. The upper end of that interval is the gene's LOEUF score, 0.74, which puts it in group 3 of 6, group 1 being the genes least tolerant of losing a copy. Missense variants: 1,014 observed, 1,088.4 expected, observed/expected ratio (o/e) 0.93, 90% interval 0.88 to 0.98. Synonymous variants: 447 observed, 424.4 expected, observed/expected ratio (o/e) 1.05, 90% interval 0.97 to 1.14.
Homologues: Orthologues: chimpanzee IRAG1 (99% identical), macaque IRAG1 (92% identical), dog IRAG1 (88% identical), rabbit IRAG1 (86% identical), pig IRAG1 (82% identical), guinea pig IRAG1 (81% identical), mouse Irag1 (79% identical), rat Irag1 (78% identical), tropical clawed frog irag1 (50% identical), zebrafish mrvi1 (41% identical). Paralogues in human: IRAG2 (12% identical).
Diseases named in the same sentence as IRAG1 in open-access papers:
IRAG1 is named in the same sentence as 36 diseases in open-access papers, as found by Europe PMC text mining. Sharing a sentence is not in itself a finding about the gene and the disease. The quoted sentences say what the papers report.
endometrial carcinoma (5 papers, 2019 to 2023). A malignant tumor arising from the epithelium that lines the cavity of the uterine body. "Like endometrial carcinoma, low expression of IRAG1 in cervical carcinoma was associated with poor overall survival." (PMID 37372987, 2023). "While the involvement of IRAG1 in ovarian carcinoma is associated with a poor prognosis, this does not apply to endometrial carcinoma." (PMID 37372987, 2023). "Thus, miR-940 regulates the progression of endometrial carcinoma by affecting the expression of IRAG1." (PMID 37372987, 2023).
migraine (4 papers, 2020 to 2023). "There were associations of IRAG1 with migraines, and combined with cervical artery dissection (CeAD), there were associations for CeAD mapped to the IRAG1 gene." (PMID 37372987, 2023). "For IRAG1, there were polymorphisms identified which are associated with migraine and CeAD, with achalasia and moyamoya syndrome, asthma, and arterial thrombosis." (PMID 37372987, 2023). "SNPs of IRAG1 were also identified in the context of migraines." (PMID 37372987, 2023).
Achalasia (2 papers, 2021 to 2023). A disorder of esophageal motility characterized by the inability of the lower esophageal sphincter to relax during swallowing and by inadequate or lacking peristalsis in the lower half of the body of the esophagus. "MRVI1—the human homologue of IRAG1—exhibits a role in the development of achalasia, which can cause injuries of the mucous membrane." (PMID 34064290, 2021). "In two achalasia patients, a homozygous nonsense mutation of IRAG1 was detected." (PMID 37372987, 2023). "This case report is consistent with previously reported data showing that microRNA (miRNA) regulates IRAG1 in esophageal SMCs in achalasia patients." (PMID 37372987, 2023). "In this context, it was shown that IRAG1 has a function in the development of achalasia." (PMID 37372987, 2023).
cervical carcinoma (2 papers, 2021 to 2023). A carcinoma arising from either the exocervical squamous epithelium or the endocervical glandular epithelium. "However, it must be mentioned that cervical cancer expression and methylation levels of IRAG1 could be effectively differentiated between cancer and healthy tissue samples." (PMID 37372987, 2023).
keratoconus (2 papers, 2009 to 2023). A degenerative, structural disorder of the eye, characterized by a cone-shaped protrusion of the cornea. "For example, an increased expression of IRAG1 in addition to two other genes was described in keratoconus, but the role of IRAG1 in this eye disease is still unclear so far." (PMID 37372987, 2023).
pulmonary hypertension (2 papers, 2020 to 2021). Increased pressure within the pulmonary circulation due to lung or heart disorder. "Echocardiography, right heart catheterization, western blotting, and immunostaining revealed that IRAG1-deficient mice develop PKG1β dependent pulmonary hypertension under normoxic conditions." (PMID 33066124, 2020).
anemia (1 paper, 2021). A reduction in the number of red blood cells, the amount of hemoglobin, and/or the volume of packed red blood cells. "Taken together, IRAG1-KO mice suffer from anemia, which is caused by (chronic) gastrointestinal bleeding." (PMID 34064290, 2021). "The present work showed that a loss of IRAG1 and the PKGIβ/IRAG1 signaling has a crucial function in the development of gastrointestinal disorders and anemia-associated splenomegaly." (PMID 34064290, 2021). "Taken together, the Irag1-deficiency caused severe anemia, as shown in the reduction of all important blood parameters." (PMID 34064290, 2021). "Global IRAG1-KO mice developed gastrointestinal bleeding, anemia-associated splenomegaly and iron deficiency." (PMID 34064290, 2021). "Taken together, Irag1-deficiency indicates that gastrointestinal bleedings lead to an iron deficient anemia, which is accompanied by splenomegaly." (PMID 34064290, 2021). "With the present work, we aimed to investigate what effect a loss of IRAG1 has on the development of anemia and splenomegaly in Irag1−/− mice." (PMID 34064290, 2021). "On the contrary, it seems very possible that the splenomegaly in IRAG1-KO mice is the result of (iron deficiency) anemia." (PMID 34064290, 2021). "Our findings are in accordance with the findings in global Prkg1-KO mice, which developed an iron deficiency caused by anemia as a follow of the gastrointestinal bleedings, which why we assume (chronic) blood loss as the direct cause of the iron deficiency in global Irag1-deficient mice." (PMID 34064290, 2021). "Irag1-deficiency led to gastrointestinal bleeding and anemia but also to splenomegaly." (PMID 34064290, 2021). "Hence, loss of IRAG1 causes gastrointestinal bleeding and, as a consequence, regenerative anemia, which is followed by an iron deficit caused by chronic blood loss." (PMID 34064290, 2021). "Old IRAG1-KO mice (age: 54–62 weeks) developed anemia and had an increase in the number of reticulocytes and the reticulocytes production index (RPI)." (PMID 34064290, 2021). "Analysis of the feces of IRAG1-KO mice exhibited gastrointestinal bleeding and anemia, which were more dominant in female mice." (PMID 34064290, 2021). "The comparison between the blood parameters of IRAG1-KO mice and global Prkg1-KO mice shows that IRAG1-KO mice suffer from a milder form of anemia." (PMID 34064290, 2021). "In this context, it was interesting to see that anemia was more prominent in female IRAG1-KO mice than in male IRAG1-KO mice." (PMID 34064290, 2021). "Further characterization of the anemia of the mRNA of livers of IRAG1-WT and IRAG1 mice were investigated regarding hepcidin (Hamp) and transferrin receptor 1 (Tfr1)." (PMID 34064290, 2021). "In the next step, several parameters were researched to characterize the type of anemia in the IRAG1-KO mice." (PMID 34064290, 2021). "These cGMP modulating substances could be also tested in further investigations regarding anemia and splenomegaly in IRAG1-KO mice." (PMID 34064290, 2021).
Arterial thrombosis (1 paper, 2023). The formation of a blood clot inside an artery. "Furthermore, IRAG1 is necessary for the cGMP-dependent inhibition of platelet activation and prevention of arterial thrombosis as well as for the inhibition of thrombin-induced adhesion of platelets to fibrinogen." (PMID 37372987, 2023).
asthma (1 paper, 2023). "Based on data from the UK Biobank study, there was an association between SNP of IRAG1 and childhood-onset asthma." (PMID 37372987, 2023).
COVID-19 (1 paper, 2024). A disease caused by infection with severe acute respiratory syndrome coronavirus 2. "MRVI1 (also IRAG1) and PCNP were identified as potential causal proteins affecting risk of COVID-19 phenotypes in this study for the first time." (PMID 40303168, 2024).
idiopathic pulmonary arterial hypertension (1 paper, 2023). A sporadic form of pulmonary arterial hypertension (PAH) characterized by elevated pulmonary arterial resistance leading to right heart failure. "Analysis of the expression of IRAG1 protein in lungs and isolated pulmonary artery of smooth muscle cells (PASMCs) of end-stage idiopathic pulmonary arterial hypertension (IPAH) revealed an increased expression of IRAG1 and PKGIβ." (PMID 37372987, 2023).
idiopathic pulmonary fibrosis (1 paper, 2023). Idiopathic pulmonary fibrosis (IPF) is a nonneoplastic pulmonary disease that is characterized by the formation of scar tissue within the lungs in the absence of any known cause. "For example, IRAG1 was demonstrated to play a significant role in the prognosis of idiopathic pulmonary fibrosis (IPF)." (PMID 37372987, 2023).
iron deficiency (1 paper, 2021). "Another indicator of an iron deficiency is the strong reduction of mRNA of the hepcidin gene in Irag1-deficient mice." (PMID 34064290, 2021). "All our results bring us to the conclusion that IRAG1-KO mice have an iron deficiency—reduced FLC levels in the liver and spleen, reduced plasma iron concentration, which indicates that iron storages are empty." (PMID 34064290, 2021).
leukemia (1 paper, 2023). A malignant (clonal) hematologic disorder, involving hematopoietic stem cells and characterized by the presence of primitive or atypical myeloid or lymphoid cells in the bone marrow and the blood. "Again, it was concluded that IRAG1 plays a significant role in the development of leukemia." (PMID 37372987, 2023). "This was already evident in the first description of IRAG1, respectively MRVI1, where it was detected in BXH2 leukemias." (PMID 37372987, 2023).
myeloid leukemia (1 paper, 2023). A clonal proliferation of myeloid cells and their precursors in the bone marrow, peripheral blood, and spleen. "Besides its involvement in the development of myeloid leukemia, IRAG1 is also important in solid tumors." (PMID 37372987, 2023). "Involvement of IRAG1 in myeloid leukemias was also demonstrated in another study investigating the extent to which the recurrent chromosomal translocations of the tyrosine kinases BCR-ABL, TEL-PDGFRB, and TEL-JAK2 regulate distinct and overlapping gene transcription profiles." (PMID 37372987, 2023). "It was concluded that IRAG1 can induce myeloid leukemia by altering the expression of a gene important for myeloid cell growth and/or differentiation, and it was suspected that IRAG1 may function as a tumor suppressor gene." (PMID 37372987, 2023).
platelet disorders (1 paper, 2023). "Hence, lack of IRAG1 or IRAG2 leads to diverse phenotypes in these organs, e.g., smooth muscle and platelet disorders or secretory deficiency, respectively." (PMID 37372987, 2023).
Splenomegaly (1 paper, 2021). Abnormal increased size of the spleen. "This leads to the assumption that it is very unlikely that a malfunction of erythrocytes caused by the loss of IRAG1 is the reason for the splenomegaly." (PMID 34064290, 2021).
systemic hypertension (1 paper, 2021). "Furthermore, global Prkg1-KO mice have a strongly reduced survival time and age-dependent systemic hypertension, in contrast to IRAG1-KO mice." (PMID 34064290, 2021).
type 1 diabetes (1 paper, 2023). "Upregulated expression of IRAG1 was associated with a bad prognosis of solid tumors, whereas the high expression level of IRAG2 could be a beneficial marker for the prognosis of lung tumors or the development of type 1 diabetes." (PMID 37372987, 2023).
cancer (5 papers, 2017 to 2025). A tumor composed of atypical neoplastic, often pleomorphic cells that invade other tissues. "Based on the present knowledge about the (patho-)physiological function of IRAG1, the currently available data indicate that IRAG1 could also be used as a diagnostic and/or prognostic marker in some fibrotic or cancer diseases." (PMID 37372987, 2023).
tumor (5 papers, 2009 to 2025). "The association of IRAG1 with tumors of the female reproductive system has been described so far." (PMID 37372987, 2023). "Regarding tumor diseases, it is noteworthy that both IRAG1 and IRAG2 were reported to possibly act as tumor suppressor genes." (PMID 37372987, 2023). "However, from these previous studies, it can be assumed that IRAG1 has different functions depending on the tumor type." (PMID 37372987, 2023). "In addition to the (patho-)physiological functions of IRAG1 described so far, it is also important in tumor diseases." (PMID 37372987, 2023).
gastrointestinal disorders (2 papers, 2021 to 2023). "Combining the known data on IRAG1 and PKGIβ suggests that a disruption of the PKGIβ/IRAG1 signaling pathway can cause the development of gastrointestinal disorders." (PMID 37372987, 2023). "In summary, a defect or loss of IRAG1 causes gastrointestinal disorders." (PMID 34064290, 2021).
IRAG1 also shares sentences with these, for which no sentence is quoted: colorectal cancer (2 papers); glioma (2); neurofibromatosis type 1 (2); breast carcinoma (1); dental caries (1); Down syndrome (1); iron deficient anemia (1); memory impairment (1); moyamoya angiopathy (1); nervous system diseases (1); neurofibromatosis (1); ovarian carcinoma (1); unstable angina (1); vasculopathies (1).